ENSG00000269755 (novel transcript)
Gene: Protein-coding gene on chromosome 19 (12,433,103 to 12,484,816, reverse strand). Ensembl gene ENSG00000269755.
Genetic constraint (gnomAD): Missense variants: 57 observed, 72.68 expected, observed/expected ratio (o/e) 0.78, 90% interval 0.63 to 0.98. Synonymous variants: 17 observed, 23.61 expected, observed/expected ratio (o/e) 0.72, 90% interval 0.49 to 1.08.